USP32P2 (ubiquitin specific peptidase 32 pseudogene 2)
Synonyms: TL132
Gene: Transcribed unprocessed pseudogene on chromosome 17 (18,513,285 to 18,519,674, reverse strand). Ensembl gene ENSG00000233327.
Diseases named in the same sentence as USP32P2 in open-access papers:
USP32P2 is named in the same sentence as 3 diseases in open-access papers, as found by Europe PMC text mining. Sharing a sentence is not in itself a finding about the gene and the disease. The quoted sentences say what the papers report.
glioma (1 paper, 2020). A benign or malignant brain and spinal cord tumor that arises from glial cells (astrocytes, oligodendrocytes, ependymal cells). "THBS3, ATP6VOE, and LINC01235 were significantly upregulated while USP32P2, RTN3, and LINC00294 were markedly downregulated in glioma compared to controls." (PMID 32978519, 2020).
Infertility (1 paper, 2024). "We note that the under-expression of USP32P2 in sperm is associated with male infertility 20, and plausibly, homozygous males for the deletion may be prone to infertility." (PMID 39315271, 2024).
USP32P2 also shares sentences with these, for which no sentence is quoted: male infertility (1 paper).